NAT10 (N-acetyltransferase 10)
Diseases named in the same sentence as NAT10 in open-access papers (continued):
Sharing a sentence is not in itself a finding about the gene and the disease.
autoimmune disease (3 papers, 2024 to 2025). A disorder resulting from loss of function or tissue destruction of an organ or multiple organs, arising from humoral or cellular immune responses of the individual to their own tissue constituents. "This review systematically explores NAT10’s multifaceted contributions to cancer, autoimmune disorders, infectious diseases, cardiovascular conditions, and metabolic syndromes." (PMID 40588654, 2025). "The ac4C modification, mediated by the only known catalytic enzyme NAT10, plays a key role in various disease processes, including infection and autoimmune diseases, and chronic diseases, and especially in tumors." (PMID 41446042, 2025). "This section systematically dissects the multifaceted roles of NAT10 and ac4C across cancer biology, autoimmune disorders, infectious diseases, and other clinical contexts." (PMID 40588654, 2025). "NAT10-mediated ac4C modification also contributes significantly to autoimmune diseases." (PMID 41446042, 2025). "Secondly, our study only recruited 20 patients with RA and 16 patients with SLE as autoimmune disease control may limit value of the predictive model based on mRNA NAT10 and N% in real clinical practice, due to N% also significantly rises in other inflammatory diseases excepts AS, RA, SLE." (PMID 38167491, 2024).
Cognitive impairment (3 papers, 2024 to 2026). Abnormal cognition is characterized by deficits in thinking, reasoning, or remembering. "Nat10 knockdown decreased Gababr1 expression and cognitive deficits." (PMID 41636018, 2026).
liver disease (3 papers, 2025 to 2026). "Additionally, NAT10 promotes metabolic dysfunction-associated steatotic liver disease by regulating lipid metabolism genes." (PMID 40588654, 2025).
lung adenocarcinoma (3 papers, 2024 to 2026). A carcinoma that arises from the lung and is characterized by the presence of malignant glandular epithelial cells. "Further bioinformatics analysis and acRIP‐qPCR confirmed the presence of ac4C acetylation checkpoints in the downstream gene TFAP2A, underscoring the role of NAT10 in lung adenocarcinoma progression." (PMID 39640362, 2024). "Immunohistochemistry analysis of tissue microarrays identified significantly higher levels of ac4C modification and its key enzyme NAT10 in lung adenocarcinoma tissues compared with adjacent normal tissues." (PMID 39640362, 2024).
pancreatic ductal adenocarcinoma (3 papers, 2023 to 2025). An infiltrating adenocarcinoma that arises from the epithelial cells of the pancreas. "Mechanistically, NAT10 enhances oncogenic mRNA stability and translation in pancreatic ductal adenocarcinoma by remodeling ac4C modified mRNAs." (PMID 38233839, 2024). "We found that: NAT10 knockdown significantly inhibited the migration and clonogenic ability of pancreatic ductal adenocarcinoma cells." (PMID 36949954, 2023). "In summary, our findings reveal a crucial role for NAT10 in pancreatic ductal adenocarcinoma, and we propose a convenient method to help diagnose and predict survival outcomes of pancreatic ductal adenocarcinoma patients." (PMID 36949954, 2023). "By knocking down NAT10, pancreatic ductal adenocarcinoma cells are inhibited from proliferating and forming colonies." (PMID 36949954, 2023). "In this study, we aimed to reveal the correlation between NAT10 expression levels and the clinical characteristics of pancreatic ductal adenocarcinoma patients." (PMID 36949954, 2023). "We collected genomic data from TCGA, GTEx and GEO databases of pancreatic ductal adenocarcinoma and then constructed NAT10 subgroup phenotypes by unsupervised clustering of NAT10-mediated gene expression levels of ac4C modifications." (PMID 36949954, 2023). "The NAT10 isoforms identified in this study can effectively predict clinical outcomes in pancreatic ductal adenocarcinoma." (PMID 36949954, 2023). "To conclude, this study examined the correlation between NAT10 expression levels and pancreatic ductal adenocarcinoma patients’ clinical characteristics." (PMID 36949954, 2023). "Pancreatic ductal adenocarcinoma tissues expressed significantly higher levels of NAT10 than normal pancreatic tissues, and the difference was statistically significant." (PMID 36949954, 2023). "Using the GEPIA website, NAT10 expression levels were analyzed between the TCGA and GTEx databases in pancreatic ductal adenocarcinoma tissues." (PMID 36949954, 2023). "A search from the Human Protein Atlas database showed that NAT10 expression was significantly higher in pancreatic ductal adenocarcinoma tissues." (PMID 36949954, 2023). "AKT activation and cell proliferation characteristics were positively correlated, suggesting that the abnormal expression of NAT10 may promote the malignant proliferation of pancreatic ductal adenocarcinoma by activating the PI3K-AKT pathway." (PMID 36949954, 2023). "NAT10 expression levels in pancreatic ductal adenocarcinoma tissues from the TCGA and GTEx databases showed that NAT10 expression levels were significantly higher in pancreatic ductal adenocarcinoma tissues than in normal pancreatic tissues." (PMID 36949954, 2023). "It is unclear, however, how NAT10 might affect pancreatic ductal adenocarcinoma." (PMID 36949954, 2023). "In pancreatic ductal adenocarcinoma, the LINC00623\/NAT10 signaling axis promotes cell proliferation, tumorigenicity, migration and invasion." (PMID 38233839, 2024). "In addition, the siRNA targeting NAT10 reduced the IC50 of gemcitabine in Capan-1 cells from 76.28μM to 23.34μM, indicating that NAT10 knockdown significantly reduced the resistance of pancreatic ductal adenocarcinoma cells to gemcitabine." (PMID 36949954, 2023).
periodontitis (3 papers, 2024 to 2025). An acute or chronic inflammatory process that affects the tissues that surround and support the teeth. "Pharmacological inhibition of NAT10 reduces bone resorption in periodontitis and inflammatory osteolysis models." (PMID 40588654, 2025). "Our study suggested Ropinirole may be a promising anti-inflammatory agent for periodontitis treatment, and NAT10 and KLF6 may be potential targets to treat periodontitis." (PMID 38689229, 2024). "Therefore, we speculated that NAT10 mediated ac4C modification may also participate in the regulation of inflammatory response in periodontitis." (PMID 38689229, 2024). "Therefore, KLF6 may be a target for periodontitis treatment, and the interaction relationship between NAT10 and KLF6 in HGFs was investigated, and the results suggested that NAT10 can elevate the mRNA levels of KLF6 and the ac4C mRNA levels of KLF6." (PMID 38689229, 2024). "Therefore, the NAT10 mediated ac4C modification mechanism may be regulated by Ropinirole in periodontitis." (PMID 38689229, 2024). "Inconsistent with this, a previous study found that overexpression of NAT10 aggravated LPS-induced inflammation through the NOX2-ROS-NF-κB axis in macrophages, and Remodelin, a specific inhibitor of NAT10, alleviated macrophage infiltration in mice with periodontitis." (PMID 40362562, 2025).
progeria (3 papers, 2018 to 2024). "NAT10‐mediated α‐tubulin (K40) acetylation (Ac‐α‐tubulin) enhances microtubule stabilization, thereby disturbing the nucleocytoplasmic shutting of cargos and causing cell dysfunction, and inhibition of NAT10 ameliorates aging features and promotes healthspan in progeria mouse model." (PMID 38686927, 2024). "Another compound, devised to inhibit acetyl transferase, NAT10 was successfully used in patients’ fibroblasts to treat progeria." (PMID 30691039, 2019). "Chemical inhibition of NAT10 as well as its knockout in a progeria mouse model (G609G phenocopy) significantly enhanced the lifespan of animals." (PMID 30691039, 2019). "Moreover, the elevated α‐tubulin (K40) acetylation mediated by NAT10 in progeria, is rescued by DOX treatment in the aorta tissues in Zmpste24 KO mice and fibroblasts." (PMID 38686927, 2024). "Collectively, our study uncovers that DOX can decelerate aging in progeria mice via counteracting IL6 expression and NAT10‐mediated acetylation of α‐tubulin." (PMID 38686927, 2024). "At the molecular level, NAT10 acts as a potential molecular target of DOX and inhibition of NAT10 likely accounts for the antiaging effect of DOX in progeria mice." (PMID 38686927, 2024). "Doxycycline decelerates aging in progeria mice and alleviates cell senescence in Zmpste24 KO MEFs and HGPS fibroblasts, probably via counteracting IL6 expression and NAT10‐mediated tubulin acetylation." (PMID 38686927, 2024).
renal clear cell carcinoma (3 papers, 2024 to 2025). "Our findings reveal that NAT10 is strongly expressed in renal clear cell tumor tissues and is closely related to tumor metastasis and the unfavorable prognosis of patients with renal clear cell carcinoma." (PMID 41189569, 2025). "The results demonstrated that overexpression of NAT10 significantly enhanced the proliferative capacity of renal clear cell carcinoma cells, whereas knockdown led to the opposite outcome." (PMID 41189569, 2025). "Recent studies have shown that N-acetyltransferase 10 (NAT10) and its mediated RNA N4-acetylcytidine (ac4C) modification are significantly upregulated in clear cell renal cell carcinoma (ccRCC) and are associated with poor prognosis in patients." (PMID 41189569, 2025). "This strongly indicates that NAT10 plays a crucial role in promoting cancer in renal clear-cell carcinoma and deserves further exploration." (PMID 41189569, 2025). "NAT10 promotes the malignant biological behavior of renal clear cell carcinoma." (PMID 41189569, 2025). "However, too date, there have been no published reports regarding the role and molecular mechanisms of NAT10 and ferroptosis in clear cell renal carcinoma." (PMID 41189569, 2025). "In summary, our results suggest that NAT10 mediates ac4C acetylation of NFE2L3 mRNA, promotes its mRNA stability, regulates the LASP1-AKT/GSK3β/β-catenin axis and promotes the progression of renal clear cell carcinoma." (PMID 40169553, 2025). "It was clearly found that in renal clear cell carcinoma ACHN and Caki1 cells, when the expression of NAT10 was silenced, the proliferation, migration and invasion capabilities of the tumor were significantly reduced." (PMID 41189569, 2025).
rheumatoid arthritis (3 papers, 2024 to 2025). A chronic, systemic autoimmune disorder characterized by inflammation in the synovial membranes and articular surfaces. "In rheumatoid arthritis (RA), elevated levels of NAT10 and ac4C were found in synovium from RA patients." (PMID 40588654, 2025). "We demonstrated that the mRNA level of NAT10 in PBMC from patients with new onset AS was significantly decreased than that in healthy controls (HC), rheumatoid arthritis (RA) and SLE, and decreased NAT10 negatively correlated with the activity of AS." (PMID 38167491, 2024).
Stroke (3 papers, 2021 to 2025). Sudden impairment of blood flow to a part of the brain due to occlusion or rupture of an artery to the brain. "NAT10/ac4C upregulates Fn14 in hypothalamic neurons, activates NF-κB to mediate central post-stroke pain." (PMID 41446042, 2025). "A UMD-GEOS Study comparing subjects who had stroke at the age 15–49 years with non-stroke controls found significant NAT10 gene burden in early-onset small vessel stroke." (PMID 35052389, 2021).
thrombosis (3 papers, 2023 to 2026). "Strikingly, inhibition of NAT10 attenuates the formation of thrombosis in DVT mice." (PMID 41467352, 2026). "To validate the function of NAT10 in DVT, we pretreated DVT mice with Remodelin (a small molecule inhibitor of NAT10) and found that the NAT10 inhibitor ameliorated the formation of thrombosis." (PMID 41467352, 2026). "All these data suggest that inhibition of NAT10 reduces HMOX1 expression and attenuates ferroptosis, thereby mitigating endothelial dysfunction and the formation of thrombosis in DVT mice." (PMID 41467352, 2026). "Collectively, our data elucidate that downregulation of NAT10 mitigates endothelial ferroptosis and prevents DVT formation and progression by modulating HMOX1 expression, which offers a potential novel strategy for the prevention and treatment of thrombosis in DVT." (PMID 41467352, 2026).
ankylosing spondylitis (2 papers, 2024 to 2025). An autoimmune chronic inflammatory disorder characterized by inflammation in the vertebral joints of the spine and sacroiliac joints. "In ankylosing spondylitis, NAT10 mRNA together with neutrophil percentages could be employed to construct a novel predictive model to distinguish new-onset ankylosing spondylitis patients from RA and SLE." (PMID 40588654, 2025). "However, the role of N-acetyltransferase 10 (NAT10) in ankylosing spondylitis (AS) is still poorly elaborated." (PMID 38167491, 2024).
cholangiocarcinoma (2 papers, 2024 to 2025). A carcinoma that arises from the intrahepatic biliary tree (intrahepatic cholangiocarcinoma) or from the junction, or adjacent to the junction, of the right and left hepatic ducts (hilar cholangiocarcinoma). "By binding to CCL2 messenger RNA, NAT10 escalates the expression level of the CCL2 protein within intrahepatic cholangiocarcinoma and in their extracellular matrix." (PMID 40588654, 2025). "Circular RNA circMAST1 competitively binds to NAT10 and obstructing NAT10-mediated ac4C modification on Yes-associated protein (YAP) mRNA, which accelerates YAP mRNA degradation and subsequently curtails tumor advancement in cholangiocarcinoma." (PMID 40588654, 2025).
Cirrhosis (2 papers, 2023 to 2026). A chronic disorder of the liver in which liver tissue becomes scarred and is partially replaced by regenerative nodules and fibrotic tissue resulting in loss of liver function. "In particular, high expression of NAT10 is associated with hepatitis, cirrhosis, and poor prognosis in patients with HCC." (PMID 36765042, 2023).
colitis (2 papers, 2025). Inflammation of the colon. "We commenced by isolating naïve CD4+ T cells from both WT and Nat10 cKO mice, and then transferred them separately into Rag1−/− recipient mice, thereby inducing an adoptive transfer colitis model." (PMID 40038243, 2025). "In order to explore the role of NAT10 in modulating IgA-associated inflammatory conditions, we employed a DSS-induced acute colitis model to mimic the clinical progression of IBD." (PMID 40615576, 2025). "Our further analysis revealed that the deficiency of NAT10 led to a disruption of T cell development at steady state, and identified a pivotal role for NAT10 in preserving the pathogenicity of naïve CD4+ T cells to induce adoptive transfer colitis." (PMID 40038243, 2025). "Besides, Nat10-deficient naïve CD4+ T cells failed to induce adoptive transfer colitis." (PMID 40038243, 2025). "The heightened apoptosis in the absence of Nat10 could be a critical factor contributing to the diminished presence of these cells in the lymphatic organs, thus reducing their capacity to induce adoptive transfer colitis." (PMID 40038243, 2025).
colorectal tumor (2 papers, 2025 to 2026). "To further investigate the effect of Nat10 on the CRC TME, we isolated colorectal tumor tissues from Nat10fl/fl and Nat10cKO mice and performed single-cell RNA-seq (scRNA-seq)." (PMID 41542770, 2026).
endothelial dysfunction (2 papers, 2025 to 2026). In vascular diseases, endothelial dysfunction is a systemic pathological state of the endothelium (the inner lining of blood vessels) and can be broadly defined as an imbalance between vasodilating and vasoconstricting substances produced by (or acting on) the endothelium. "NAT10 overexpression inhibits EndMT in hypertension, which is partly due to the inhibition of endothelial dysfunction, whereas NAT10 inhibition has the opposite effect." (PMID 41254488, 2025). "Overall, our data indicated that NAT10 inhibitor induces EndMT in hypertension, which is partly due to the endothelial dysfunction." (PMID 41254488, 2025). "In summary, our study revealed that NAT10-induced ac4C acetylation of AdipoR1 mRNA inhibits EndMT in hypertension, which is partly due to the inhibition of endothelial dysfunction via increased mitochondrial biogenesis and function." (PMID 41254488, 2025). "Remodelin was used to determine the effect of NAT10 inhibition on endothelial dysfunction and EndMT of HUVECs." (PMID 41254488, 2025). "Mechanistically, NAT10 inhibited endothelial dysfunction in hypertension through increased AdipoR1 mRNA ac4C acetylation." (PMID 41254488, 2025). "We found that NAT10 overexpression inhibits EndMT in hypertension, which is partly due to the inhibition of endothelial dysfunction, whereas NAT10 inhibition has the opposite effect." (PMID 41254488, 2025). "In vitro assays revealed that NAT10 overexpression inhibits Ang II-induced endothelial dysfunction and EndMT, whereas NAT10 knockdown has the opposite effect." (PMID 41254488, 2025). "The effects of NAT10 on EndMT and endothelial dysfunction were measured via a gain-of-function assay." (PMID 41254488, 2025). "Furthermore, sh-NAT10 triggered SM22α and N-cadherin expression but decreased CD31 and VE-cadherin levels in Ang II-treated HUVECs, indicating that NAT10 knockdown increases Ang II-induced endothelial dysfunction and EndMT in HUVECs." (PMID 41254488, 2025). "We subsequently explored whether NAT10 inhibited endothelial dysfunction in hypertension in an AdipoR1-dependent manner." (PMID 41254488, 2025). "Thus, we observed that NAT10 overexpression inhibits EndMT in hypertension, which is partly due to the inhibition of endothelial dysfunction." (PMID 41254488, 2025). "Moreover, NAT10 overexpression inhibits EndMT in hypertension, which is partly due to the inhibition of endothelial dysfunction." (PMID 41254488, 2025). "The current data highlighted the molecular mechanisms of NAT10-induced ac4C acetylation and implied that the NAT10-AdipoR1 axis might be the therapeutic target to inhibit endothelial dysfunction and EndMT in hypertension." (PMID 41254488, 2025). "Moreover, OE-NAT10 increased the proliferation, migration, and angiogenesis abilities of Ang II-treated HUVECs, indicating that NAT10 overexpression inhibits Ang II-induced endothelial dysfunction and EndMT in HUVECs." (PMID 41254488, 2025). "Together, these data indicated that inhibition of NAT10 reduced HMOX1 expression and alleviated ferroptosis, thereby attenuating endothelial dysfunction." (PMID 41467352, 2026). "Mechanistic studies indicated that NAT10 facilitated the N4-acetylcytidine modification of HMOX1 (heme oxygenase 1), which enhanced its mRNA stability, leading to the accumulation of ferrous ions, and exacerbating endothelial dysfunction in DVT." (PMID 41467352, 2026). "Despite these advancements, the relationships among NAT10, endothelial dysfunction, and EndMT in hypertension have not yet been reported." (PMID 41254488, 2025). "Herein, we explored the effect of NAT10-induced ac4C acetylation on endothelial dysfunction and EndMT in hypertension and clarified the mechanism through which the NAT10/ac4C/AdipoR1/PGC-1α axis inhibits endothelial dysfunction via the regulation of mitochondrial biogenesis and function." (PMID 41254488, 2025).